CRYBG3 (crystallin beta-gamma domain containing 3)
Description:
[Isoform vlAKAP]: Anchoring protein that mediates the subcellular compartmentation of protein kinase A (PKA).
Synonyms: vlAKAP; DKFZp667G2110
Tractability: Antibody: the Human Protein Atlas places it where antibodies can reach. PROTAC: ubiquitination databases record sites on it; its protein half-life has been measured.
Gene: Protein-coding gene on chromosome 3 (97,822,011 to 97,944,984, forward strand). Ensembl gene ENSG00000080200.
Subcellular location (Human Protein Atlas): Plasma membrane; Primary cilium
Gene Ontology:
Molecular function: protein kinase A binding; structural constituent of eye lens
Biological process: lens development in camera-type eye; visual perception
Cellular component: protein-containing complex
Genetic constraint (gnomAD): Loss-of-function variants: 104 observed, 196.42 expected, observed/expected ratio (o/e) 0.53, 90% interval 0.45 to 0.62. The upper end of that interval is the gene's LOEUF score, 0.62, which puts it in group 2 of 6, group 1 being the genes least tolerant of losing a copy. Missense variants: 2,997 observed, 3,139.7 expected, observed/expected ratio (o/e) 0.95, 90% interval 0.93 to 0.98. Synonymous variants: 1,021 observed, 1,110.1 expected, observed/expected ratio (o/e) 0.92, 90% interval 0.87 to 0.97.
Homologues: Orthologues: chimpanzee CRYBG3 (99% identical), macaque ARL6 (91% identical), dog CRYBG3 (73% identical), pig CRYBG3 (72% identical), rabbit CRYBG3 (69% identical), rat Crybg3 (63% identical), mouse Crybg3 (62% identical). Paralogues in human: CRYBG1 (14% identical), CRYBG2 (11% identical), CRYBA1 (2% identical), CRYBB1 (2% identical), CRYBA4 (2% identical), CRYBB3 (2% identical), CRYBB2 (2% identical), CRYBA2 (2% identical), CRYGD (2% identical), CRYGA (2% identical), CRYGC (2% identical), CRYGB (2% identical), and 2 more.
Diseases named in the same sentence as CRYBG3 in open-access papers:
CRYBG3 is named in the same sentence as 6 diseases in open-access papers, as found by Europe PMC text mining. Sharing a sentence is not in itself a finding about the gene and the disease. The quoted sentences say what the papers report.
lung carcinoma (8 papers, 2019 to 2023). "We found that loss of endogenous lncRNA CRYBG3 increased lung cancer cell invasiveness and metastatic ability, however, this was counteracted by concomitant knockdown of TAZ." (PMID 35246511, 2022). "Deep sequencing techniques during cancer-radiation approach therapies showed upregulation of LNC CRYBG3 in several lung cancer cell lines, suggesting that it is a radiosensitive induced lncRNA." (PMID 35447891, 2022). "Crystallin Beta-Gamma Domain Containing 3 (CRYBG3) is a another upregulated lncRNA resulting in genomic instability in A549 lung cancer cells." (PMID 34692550, 2021). "Our previous study identified a novel lncRNA LNC CRYBG3 that was up-regulated in lung cancer and inducible by ionizing radiation." (PMID 33809929, 2021). "Herein, we revealed that LNC CRYBG3 expression was remarkably increased in patient lung cancer tissues, particularly in metastatic tumors." (PMID 33809929, 2021). "In our previous study, LNC CRYBG3 was found to be highly expressed in the lung cancer tissues compared to normal lung tissues." (PMID 33809929, 2021). "Furthermore, lncRNA CRYBG3 exerted a tumor-suppressor function by inhibiting the proliferation, invasion, and metastasis of lung cancer cells through YAP/TAZ." (PMID 35246511, 2022). "LNC CRYBG3 can bind to eEF1A1, which is not only a translation factor, but also a pleiotropic protein that is highly expressed in human tumors, including breast, ovarian, and lung cancers." (PMID 33809929, 2021). "Based on these results, LNC CRYBG3 may be a potential target for lung cancer prevention and treatment in the clinic." (PMID 33809929, 2021). "Similarly, LNC CRYBG3 levels were also determined in several lung cancer cell lines, including HCC827, A549, H460, and H1299, and in the normal lung cell lines Beas-2B and HSAEC1-KT." (PMID 33809929, 2021). "More elevated LNC CRYBG3 expression was found in lung cancer cell lines than in normal cell lines." (PMID 33809929, 2021). "In addition, our previous study suggested that LNC CRYBG3 is a regulator of glycolysis and that its overexpression promotes lung cancer cell proliferation." (PMID 33809929, 2021). "The present study found that LNC CRYBG3 can combine with eukaryotic translation elongation factor 1 alpha (eEF1A1), which is not only a translation factor, but also a pleiotropic protein that is highly expressed in human tumors, including breast, ovarian, and lung cancers." (PMID 33809929, 2021). "BUB3 directly binds to LNC CRYBG3 and interrupts its interaction with CDC20 to result in aneuploidy, thus promoting the tumorigenesis and metastasis of lung cancer cells." (PMID 36787437, 2023). "The present study found that LNC CRYBG3 overexpression increased MDM2 levels and led to lung cancer cell metastasis, while LNC CRYBG3 depletion suppressed MDM2 expression and metastasis." (PMID 33809929, 2021). "Ionizing radiation-induced lncRNA CRYBG3 can blunt YAP/TAZ activity through interference with mechanotransduction, resulting in the inhibition of cell proliferation, invasion, and metastasis of lung cancer cells." (PMID 35246511, 2022). "In lung cancer cell lines, it is reported that lncRNA CRYBG3 regulates glycolysis rather than oxidative phosphorylation to increase lung cancer cell proliferation through interacting with LDHA." (PMID 31850189, 2019).
virus infection (1 paper, 2024). "As an important protein structure regulator gene, CRYBG3 is likely to be involved in the regulation of platelet size and volume, which play an important role in blood coagulation and inflammatory response during virus infection." (PMID 39408741, 2024).
tumor (7 papers, 2021 to 2025). "In vivo, we found that loss of lncRNA CRYBG3 could power the tumor initiation and metastasis ability, but this was abolished by concomitant deplete TAZ." (PMID 35246511, 2022). "LncRNA CRYBG3-deficient xenograft revealed an increase in tumor stiffness." (PMID 35246511, 2022). "CRYBG3 was recently found to be a potent tumor-promoting lncRNA that is involved in inducing aneuploidy and promoting tumor metastasis in NSCLC." (PMID 35757505, 2022). "In vivo, constitutive knockdown of lncRNA CRYBG3 in xenograft displayed a rapid tumor growth and increased tumor volume, but this was blunted by concomitant depletion of TAZ." (PMID 35246511, 2022). "The findings presented here demonstrate that ionizing radiation leads to a severe reduction of tumor-tissue stiffness that is mediated by IR-induced expression of lncRNA CRYBG3." (PMID 35246511, 2022). "CRYBG3 has recently been identified as a powerful tumor-promoting lncRNA that plays a role in NSCLC tumor spread and aneuploidy." (PMID 36362424, 2022). "Our data suggest that lncRNA CRYBG3 induced by ionizing radiation impairs the mechanosignaling pathway, thereby regulating tumor growth and metastasis through the activity of mechanotransduction effector molecules YAP/TAZ." (PMID 35246511, 2022). "Conversely, we hypothesized that depletion of lncRNA CRYBG3 might lead to increased tumor stiffness." (PMID 35246511, 2022). "Moreover, overexpression of lncRNA CRYBG3 in tumor tissues also impeded the phosphorylation of MLC2, a marker of tissue contractility and cellular mechanotransduction." (PMID 35246511, 2022). "Finally, our research highlights lncRNA CRYBG3 as a potential new target for tumor diagnosis and treatment." (PMID 35246511, 2022). "We found that lncRNA CRYBG3 overexpression decreased tumor-tissue stiffness." (PMID 35246511, 2022). "In conclusion, the LNC CRYBG3/eEF1A1/MDM2/MTBP axis is a novel signaling pathway regulating tumor metastasis and may be a potential therapeutic target for NSCLC treatment." (PMID 33809929, 2021). "Thus, we explored if the increased lncRNA CRYBG3 expression might have a softening effect on tumor cell plasticity." (PMID 35246511, 2022). "Next, we assessed whether lncRNA CRYBG3 affects tumor invasion and metastasis through YAP/TAZ." (PMID 35246511, 2022). "Our research proposes that lncRNA CRYBG3 is a mediator of radiotherapy through its control of cancer-tissue mechanotransduction and wiring YAP/TAZ activity to control tumor growth and metastasis." (PMID 35246511, 2022).
cancer (3 papers, 2014 to 2024). A tumor composed of atypical neoplastic, often pleomorphic cells that invade other tissues. "MEGM DEGs are mainly associated with the topics ‘cancer’, ‘neuro’ and ‘eye & retina’ or two combined topics like ‘cancer and neuro’ (SEMA3C, ROR1, EPHA7, GDNFR) or ‘eye & retina and neuro’ (PRDM8, CRYBG3)." (PMID 39695086, 2024).
CRYBG3 also shares sentences with these, for which no sentence is quoted: metastatic tumors (1 paper); non-small cell lung carcinoma (1).